OSR2 (odd-skipped related transciption factor 2)
Description:
May be involved in the development of the mandibular molar tooth germ at the bud stage.
Synonyms: FLJ90037
Tractability: Antibody: the Human Protein Atlas places it where antibodies can reach.
Gene: Protein-coding gene on chromosome 8 (98,940,116 to 98,952,336, forward strand). Ensembl gene ENSG00000164920.
Subcellular location: Nucleus
Subcellular location (Human Protein Atlas): Plasma membrane; Nucleoplasm
Gene Ontology:
Molecular function: protein binding; sequence-specific double-stranded DNA binding; DNA-binding transcription activator activity, RNA polymerase II-specific; DNA-binding transcription factor activity, RNA polymerase II-specific; RNA polymerase II transcription regulatory region sequence-specific DNA binding; sequence-specific DNA binding
Biological process: bone morphogenesis; cell differentiation; chondrocyte differentiation; embryo development ending in birth or egg hatching; embryonic digit morphogenesis; embryonic forelimb morphogenesis; embryonic hindlimb morphogenesis; embryonic skeletal joint development; embryonic skeletal joint morphogenesis; embryonic skeletal limb joint morphogenesis; embryonic skeletal system morphogenesis; eyelid development in camera-type eye; head development; mesonephros development; metanephros development; middle ear morphogenesis; negative regulation of transcription by RNA polymerase II; odontogenesis; osteoblast proliferation; pattern specification process; positive regulation of bone mineralization; positive regulation of cell population proliferation; positive regulation of DNA-templated transcription; positive regulation of epithelial cell proliferation; positive regulation of gene expression; and 4 more
Cellular component: nucleus
Genetic constraint (gnomAD): Loss-of-function variants: 7 observed, 19.98 expected, observed/expected ratio (o/e) 0.35, 90% interval 0.2 to 0.66. The upper end of that interval is the gene's LOEUF score, 0.66, which puts it in group 2 of 6, group 1 being the genes least tolerant of losing a copy. Missense variants: 299 observed, 416.35 expected, observed/expected ratio (o/e) 0.72, 90% interval 0.65 to 0.79. Synonymous variants: 177 observed, 179.68 expected, observed/expected ratio (o/e) 0.99, 90% interval 0.87 to 1.12.
Homologues: Orthologues: chimpanzee OSR2 (100% identical), rat Osr2 (99% identical), dog OSR2 (99% identical), pig OSR2 (99% identical), rabbit OSR2 (99% identical), mouse Osr2 (98% identical), tropical clawed frog osr2 (96% identical), macaque OSR2 (81% identical), guinea pig OSR2 (81% identical), zebrafish osr2 (55% identical), Caenorhabditis elegans odd-1 (29% identical), Drosophila melanogaster drm (14% identical). Paralogues in human: OSR1 (57% identical).
Diseases named in the same sentence as OSR2 in open-access papers:
OSR2 is named in the same sentence as 28 diseases in open-access papers, as found by Europe PMC text mining. Sharing a sentence is not in itself a finding about the gene and the disease. The quoted sentences say what the papers report.
cleft palate (3 papers, 2017 to 2025). Cleft palate is a fissure type embryopathy that affects the soft and hard palate to varying degrees. "Previous studies showed that deletion of Osr2, Fgf10, and Shh all lead to cleft palate during normal palatal development, and they play an important role in the regulation of palatal protrusive cell proliferation." (PMID 40429955, 2025).
gastric cancer (3 papers, 2016 to 2022). A primary or metastatic malignant neoplasm involving the stomach. "OSR2 has been identified as a potential biomarker for survival prognosis in muscle invasive bladder cancer, and its hypermethylation is a diagnostic marker in gastric cancer." (PMID 36185403, 2022).
abortion (2 papers, 2022 to 2024). the ending of pregnancy by removing a fetus or embryo before it can survive outside the uterus. "Decreased OSR2 level was observed in the patients with recurrent spontaneous abortion and knockdown of OSR2 impairs the decidualization process in the human endometrial stromal cells (EnSCs)." (PMID 38536963, 2024).
lung adenocarcinoma (2 papers, 2024 to 2026). A carcinoma that arises from the lung and is characterized by the presence of malignant glandular epithelial cells. "Of these genes, we identified OSR2 as a potential oncogene which was epigenetically dysregulated upon ECS exposure in our mouse study as well as in human lung adenocarcinoma dataset and upregulated in the human lung adenocarcinoma." (PMID 39273313, 2024).
prostate carcinoma (2 papers, 2023 to 2024). A carcinoma that arises from epithelial cells of the prostate gland. "We also provide evidence that the mammalian homologs of Hyd (UBR5), Lin (LINS1), and Bowl (OSR1/2) constitute an analogous protein degradation pathway in human cells, and that OSR2 promotes prostate cancer tumorigenesis." (PMID 39137945, 2024). "Remarkably, OSR2 overexpression in two advanced prostate cancer cell lines, CWR22Rv and PC3, significantly enhanced the growth of these tumor cells." (PMID 39137945, 2024). "We also provide evidence that the mammalian homologs of Hyd (UBR5, known to be recurrently dysregulated in various human cancers), Lin (LINS1), and Bowl (OSR1/2) constitute an analogous protein degradation pathway in human cells, and that OSR2 promotes prostate cancer tumorigenesis." (PMID 39137945, 2024). "All this suggests that it is unlikely that JMJD2D impinges in a meaningful way on the oncogenic potential of prostate cancer cells through modulating the expression of GLIS3, RSPO3, NPR1 or OSR2." (PMID 38045004, 2023). "This would be consistent with the notion that methylation of JMJD2D could promote prostate cancer development through upregulation of CBLC and METTL27 as well as through downregulation of COL4A5, GLIS3, NPR1, OSR2, PLAGL1 and RSPO3." (PMID 38045004, 2023).
cervical squamous cell carcinoma (1 paper, 2021). A squamous cell carcinoma arising from the cervical epithelium. "13.8% of 297 cervical squamous cell carcinoma cases revealed that genetic alterations in the five-gene signature with a low frequency of ALDH1A2 (1.3%), OSR2 (1%), GRIA4 (4%), GATA4 (1%), and IRX4 (7%)." (PMID 34745985, 2021).
chondrosarcoma (1 paper, 2016). A malignant cartilaginous matrix-producing mesenchymal neoplasm arising from the bone and soft tissue. "The Osr2-Cre;Fam20Bflox/flox mice showed chondrosarcoma in the knee joint and remarkable defects of postnatal ossification in the long bones." (PMID 27405802, 2016). "Given that administering WNT inhibitor to the Osr2-Cre;Fam20Bflox/flox mice did not significantly rescue the chondrosarcoma phenotype, we envision that the chondrosarcoma may be associated with molecular changes of other pathway(s)." (PMID 27405802, 2016).
endometrial cancer (1 paper, 2023). Primary or metastatic malignant neoplasm involving the endometrium (mucous membrane that lines the endometrial cavity). "However, OSR2 expression, decreased only by kaempferol treatment, is commonly downregulated in endometrial cancer suggesting that some transcripts associated with risk have varied expression patterns as a result of kaempferol treatment." (PMID 36986136, 2023).
endometriosis (1 paper, 2021). The growth of functional endometrial tissue in anatomic sites outside the uterine body. "Notably, in the ectopic endometrial cell group of endometriosis, tumor suppressor genes such as OSR2 were down-regulated compared with the eutopic endometrial cell group." (PMID 33868805, 2021).
Eyelid malformation (1 paper, 2021). "This might be due to the fact that the targets of FOXL2 (with respect to eyelid malformations) may be much more than OSR2." (PMID 33796131, 2021).
hypophosphatasia (1 paper, 2021). Hypophosphatasia (HPP) is a rare heritable metabolic disorder characterized by defective mineralization of bone and/or teeth in the presence of reduced activity of unfractionated serum alkaline phosphatase (ALP). "It is worth noticing that the orientation of hypophosphatasias was intraversive in the WT soft palates, but extraversive in the Osr2-creKI;pMes-Noggin soft palates." (PMID 34557486, 2021).
lung carcinoma (1 paper, 2024). "In addition, siRNA knockdown was employed to probe the functional roles of ZFPM2 and OSR2 in lung cancer cell proliferation." (PMID 39273313, 2024). "Importantly, the knockdown of OSR2 in human adenocarcinoma (H838) cells significantly inhibited cell proliferation as compared to the non-targeting siRNA group, suggesting a possible oncogenic role of OSR2 in lung cancer." (PMID 39273313, 2024). "These genes include GRIA3, TAF7L, ARL14, PCDHGA9, MDGA1, ZFPM2, OSR2, TMC8/TMC6, HCN2, and CDK5R2, which are likely to be relevant in human lung cancer and are also epigenetically deregulated upon exposure to ECS in our animal study." (PMID 39273313, 2024).
prostate tumors (1 paper, 2023). "On the other hand, we focused on six genes (COL4A5, GLIS3, NPR1, OSR2, PLAGL1 and RSPO3) that were significantly downregulated in human prostate tumors as well as upregulated in DU145-R427 cells, suggesting that these genes might negatively interfere with prostate tumorigenesis." (PMID 38045004, 2023).
tumor (14 papers, 2016 to 2026). "Immune infiltration correlation and pan-cancer single-cell transcriptomics analysis revealed a strong association between OSR2 expression and cancer-associated fibroblasts (CAFs) in the tumor microenvironment (TME)." (PMID 42112349, 2026). "Our analysis systematically evaluated OSR2 expression patterns, prognostic significance, and its correlations with tumor mutational burden (TMB), microsatellite instability (MSI), immune infiltration and immune checkpoint gene expression." (PMID 42112349, 2026). "Cox hazard ratio analysis corroborated this finding, revealing increased risks of antiandrogen-resistant tumor progression associated with elevated OSR2 expression." (PMID 39137945, 2024). "Osr2 is preferentially upregulated in deeply exhausted, tumor-specific CD8+ T cells through the combined input of TCR activation and mechanical stress transmitted via the Piezo1–calcium–CREB pathway." (PMID 41551882, 2026). "The transcription factor Osr2 integrates biomechanical signals to promote the terminal exhaustion of tumor-specific CD8+ T cells." (PMID 41194917, 2025). "Odd-skipped related transcription factor 2 (OSR2), a zinc finger TF from the odd-skipped family, is markedly overexpressed in tumor-specific CD8+ T cells subjected to biomechanical stress." (PMID 40693464, 2025). "PIEZO1 can augment CD8+ T cell exhaustion via activation of the transcription factor OSR2 in the tumor microenvironment." (PMID 40454475, 2025). "Functional experiments show that deletion of Osr2 alleviates the exhaustion of tumor-specific CD8+ T cells or CAR-T cells, whereas forced overexpression of Osr2 exacerbates CD8+ T cell exhaustion in solid tumor models." (PMID 41194917, 2025). "T cell–specific OSR2-KO mice demonstrated reduced exhaustion of tumor-infiltrating CD8+ T cells and CAR-T cells in the MC38 colon tumor mouse model, resulting in enhanced cell proliferation and tumor control." (PMID 40693464, 2025). "Experiments have demonstrated that Osr2 integrates biomechanical signaling and promotes the terminal exhaustion of tumor-reactive CD8+ T cells." (PMID 41282026, 2025). "Tumour-associated immune cells, such as Osr2, which promotes CD8 + T cell exhaustion, also play a crucial role in tumour stiffness and immune evasion." (PMID 39881364, 2025). "Differential expression analysis revealed that the levels of ALDH1A2 and OSR2 were significantly reduced in the tumor tissues as compared to the normal tissues." (PMID 34745985, 2021). "As expected, differential expression analysis revealed that the levels of ALDH1A2 and OSR2 were significantly reduced in the tumor tissues as compared to the normal tissues." (PMID 34745985, 2021). "Functional enrichment analysis suggested that OSR2 may promote tumor progression through induction of epithelial-mesenchymal transition (EMT)." (PMID 42112349, 2026). "In terms of upregulated DEGs, seven genes (ABI3BP, CTSG, DPP4, CCL18, OSR2, GRIA3, MMP2) demonstrated reduced expression in tumor compared to normal tissue." (PMID 39062832, 2024). "Despite aberrant promoter hypermethylation of ALDH1A2, OSR2, GATA4, and GRIA4 have already been reported in several human tumor cell lines or tumor tissues." (PMID 34745985, 2021). "A pan-cancer analysis with 10,967 tumor samples in 32 TCGA cohorts revealed that a low frequency of ALDH1A2 (1.4%), OSR2 (5%), GRIA4 (3%), GATA4 (4%), and IRX4 (5%) was genetically altered." (PMID 34745985, 2021). "Moreover, when we stratified the TNM stages and analyzed the diagnostic value between those two methods in each stage, we found that detection of OSR2, VAV3, and PPFIA3 hypermethylation showed significantly higher sensitivity than that of serum tumor markers." (PMID 27143812, 2016). "In solid tumor models, the absence of Osr2 can alleviate the exhausted state of transferred tumor-specific T cells and enhance their control of tumors, suggesting that Osr2, as a biomechanical checkpoint, holds promise as a new target for solid tumor immunotherapy." (PMID 39342365, 2024).
tumor (continued). "Of note, induction of OSR2 only occurred in exhausted T cells in the tumor microenvironment and not in response to chronic viral infection, which has an absence of substantial mechanical stress, suggesting that upregulation of OSR2 may not be a universal mechanism of T cell exhaustion." (PMID 40693464, 2025).
cancer (7 papers, 2018 to 2026). A tumor composed of atypical neoplastic, often pleomorphic cells that invade other tissues. "OSR2 emerges as a promising prognostic biomarker and potential therapeutic target for human cancers; additionally, it may act as a reliable predictor of immunotherapy response in LUAD." (PMID 42112349, 2026). "KLHL6, HAO2, and OSR2 have been shown to be involved in the prognosis of other cancers." (PMID 36185403, 2022). "Moreover, low cancer specificity of OSR2 was found based on the literature review." (PMID 34745985, 2021).
infection (1 paper, 2022). The state of being infected such as from the introduction of a foreign agent such as serum, vaccine, antigenic substance or organism. "As expected, infection with OSR2-overexpression lentivirus, rather than control virus, at least partly rescued the downregulated IGFBP1 expression level upon MAX knockdown." (PMID 35146559, 2022).
OSR2 also shares sentences with these, for which no sentence is quoted: adenocarcinoma (1 paper); Cohen syndrome (1); heart failure (1); microcephaly (1); neutropenia (1); ovarian carcinoma (1); prostate adenocarcinoma (1); Retinal dystrophy (1); Stroke (1); tooth agenesis (1); Truncal obesity (1); Wilms tumor (1).